AGRN (agrin)
Diseases named in the same sentence as AGRN in open-access papers (continued):
Sharing a sentence is not in itself a finding about the gene and the disease.
breast carcinoma (5 papers, 2015 to 2023). "Increased cytoplasmic distribution and enhanced phosphorylation of YAP at Ser127 leading to its proteosomal degradation are observed after agrin knockdown through siRNA or shRNA in liver or breast cancer cells, respectively." (PMID 35174224, 2021). "In vivo, mouse xenografts also showed a higher expression of Agrin in the liver (Hep3B) tumours compared with MCF7 cell breast carcinoma." (PMID 25630468, 2015). "Supernatants of HCC cell lines (MHCC-LM3 and Hep3B), a breast cancer cell line SkBr-3 and control MIHA cells were tested for Agrin secretion." (PMID 25630468, 2015).
Cirrhosis (5 papers, 2015 to 2024). A chronic disorder of the liver in which liver tissue becomes scarred and is partially replaced by regenerative nodules and fibrotic tissue resulting in loss of liver function. "It will be interesting to find out at what stage of cirrhosis and cancer development does agrin expression become prominent?" (PMID 29415512, 2018). "In fact, agrin accumulates in the liver of patients with cirrhosis, and has been proposed to play a stimulatory role in neoangiogenic processes, and a supportive role in bile ductule proliferation." (PMID 26317806, 2015). "From our study, elevated levels of agrin might be predictive of cirrhosis but may distinguish cirrhosis-induced HCC." (PMID 39123447, 2024). "In vivo experiment suggested sorafenib could alleviate the hepatocarcinogenesis mediated through agrin secretion and could be potential candidate for treatment of cirrhosis." (PMID 29285255, 2017). "Studies have shown accumulation of agrin in cirrhosis and HCC both in humans and rats." (PMID 29285255, 2017). "In our study, non-alcohol drinkers with HCC had higher agrin levels, probably indicating that other factors like genetics, viral exposure, and non-alcoholic steatohepatitis might be contributing to cirrhosis and thus HCC and might not be due to only alcohol exposure." (PMID 39123447, 2024).
oral cancer (5 papers, 2014 to 2023). "Our study showed, for the first time, a negative regulation on oral cancer-associated events by either targeting chondroitin sulfate content or agrin and perlecan levels." (PMID 25506919, 2014). "In this study, we showed for the first time that agrin and perlecan are highly expressed in OSCCs, and the function of these proteins in oral cancer associated processes was investigated." (PMID 25506919, 2014). "Most oral cancer cell lines secreted high levels of agrin (band having a molecular weight of ~ 72 kDa)." (PMID 29872149, 2018). "Taken together, the data suggest that silencing agrin in oral cancer cells results in an impairment of in vitro proliferative and invasive growth programmes." (PMID 29872149, 2018). "We found that invasive oral carcinomas and premalignant lesions show a strong expression of agrin compared with benign lesions." (PMID 29872149, 2018). "In this research, the histopathological data cumulatively support the pathophysiological role of agrin in oral cancer progression." (PMID 29872149, 2018). "Altogether, our results demonstrate that agrin is a histological marker for the progression of oral cancer and is a strong therapeutic target candidate for both premalignant and OSCC lesions." (PMID 29872149, 2018). "In this study, we have demonstrated that agrin and perlecan play a role in the oral cancer cell movement by silencing agrin and perlecan, which promoted a strongly reduced in the ability of SCC-9 and SCC-9 LN-1 cell line to migrate and to adhere to matrigel." (PMID 25506919, 2014). "Two of the major basement membrane proteoglycans, agrin and perlecan, were investigated in this study regarding their role in oral cancer." (PMID 25506919, 2014). "In the present study, we focused on understanding the role of the proteoglycans agrin and perlecan in oral cancer." (PMID 25506919, 2014). "Focussing on the dynamics of tumour progression, the Ct-agrin could then help explain the role of agrin in oral cancer." (PMID 29872149, 2018). "POFUT1 is predominantly overexpressed in colorectal metastasis (83.9%) and could O-fucosylate other protein targets than NOTCH receptors, such as AGRIN which was shown to enhance tumor progression by activating cell migration and invasion in oral cancer." (PMID 30380753, 2018). "In summary, we have identified a relevant role of agrin and perlecan in oral cancer cell adhesion, migration and cisplatin cell resistance, opening new perspectives for further investigations and targeting innovative and/or complementary therapeutic strategies." (PMID 25506919, 2014). "This clearly demonstrates the relationship between agrin and cell cycle progression promoted by FAK also in oral cancer cells." (PMID 29872149, 2018).
Alzheimer disease (4 papers, 2014 to 2024). A progressive, neurodegenerative disease characterized by loss of function and death of nerve cells in several areas of the brain leading to loss of cognitive function such as memory and language. "As Agrin was reported to drive mechanotransduction and to interact with Aβ peptides becoming part of the amyloid plaque in Alzheimer’s disease brain, it seemed to be the perfect bridge between amyloids and mechanotransduction." (PMID 38199984, 2024). "The impact of Alzheimer’s disease on membrane-bound HSPG agrin distribution has been documented since 1999; in normal brains, agrin is in the soluble fraction of detergent extracted samples, while in AD brains, agrin shifts to the insoluble fraction." (PMID 36551220, 2022). "In addition, Agrin accumulates in the brain of individuals affected by Alzheimer’s disease, specifically at the level of amyloid plaques, interacting with Aβ peptides." (PMID 38199984, 2024).
autoimmune disease (4 papers, 2012 to 2021). A disorder resulting from loss of function or tissue destruction of an organ or multiple organs, arising from humoral or cellular immune responses of the individual to their own tissue constituents. "A pathogenic role of MMP-3 dependent cleavage of agrin in neurological disorders has been suggested in addition to being associated with autoimmune diseases." (PMID 22984437, 2012). "As Agrin was reported to be expressed in T cells and promote autoimmune disease development, we further explored the effects of Agrin on TIME using TIMER and TIDE website." (PMID 35111682, 2021). "Being an autoimmune disease, MG correlates with the presence of detectable antibodies directed against the acetylcholine receptor, muscle-specific kinase, lipoprotein-related protein 4, agrin, titin, and ryanodine in the postsynaptic membrane at the NMJ." (PMID 33767779, 2021). "Furthermore, Agrin was highly expressed on the membrane of primary T cells and involved in autoimmune disease progression." (PMID 35111682, 2021). "In addition, Agrin is a key mediator in primary T cell activation in autoimmune disease." (PMID 35111682, 2021). "MG is a B-cell mediated organ-specific autoimmune disease with antibodies against the acetylcholine receptor, muscle-specific kinase (MUSK), lipoprotein-related protein 4 (LRP4), or agrin in the post-synaptic membrane at the neuromuscular junction." (PMID 32982946, 2020).
COVID-19 (4 papers, 2023 to 2024). A disease caused by infection with severe acute respiratory syndrome coronavirus 2. "With our own findings coinciding with the current literature, LGALS9, LAMP3, PRSS8 and AGRN prove to be potential biomarkers of health risk in COVID-19 patients, both individually and collectively." (PMID 39334929, 2024). "In conclusion, our study demonstrates that LGALS9, LAMP3, PRSS8 and AGRN are highly significant, differentially regulated plasma proteins found in hospitalised COVID-19 patients." (PMID 39334929, 2024). "The objective of this study was to scrutinize the potential correlation between the levels of selected myokines (myostatin, agrin, irisin, and myonectin) and the duration of rehabilitation in post-COVID-19 patients." (PMID 38672190, 2024). "We go on to show that AGRN is also differentially expressed in hospitalised COVID-19 patients and has good predictive capabilities." (PMID 39334929, 2024). "Key myokines such as myostatin, agrin, irisin, and myonectin may play pivotal roles in the pathogenesis, response to infection, and outcomes of COVID-19 patients." (PMID 38672190, 2024). "FSTL3 has been implicated as a marker of COVID-19—CVD complications; however, no SNPs were found to be significantly correlated with hospitalisation for LGALS9, LAMP3, PRSS8 or AGRN." (PMID 39334929, 2024). "The most changed components of BM included laminins (LAMB2, LAMA2, LAMC3, LAMB1, LAMC1, and LAMA5) and proteoglycans (COL18A1, HSPG2, and AGRN), with some BM specific collagens (IV, VIII, XVIII, and V collagens) remaining in COVID-19 brains, as compared with the control brains." (PMID 36609561, 2023).
Obesity (4 papers, 2015 to 2024). Accumulation of substantial excess body fat. "Epigenetic studies also suggest a role for AGRN in human obesity as a link between DNA methylation and AGRN was found in a study involving obese and healthy individuals." (PMID 36613828, 2022). "Agrin is an important component of the glomerular basement membrane and renal tubules, which may be damaged in obesity." (PMID 39409098, 2024).
pancreatic cancer (4 papers, 2022 to 2025). "Thus, it remains uncertain whether loss or preservation of agrin expression is as clear-cut for the distinction between well-differentiated cholangiocarcinomas and metastatic pancreatic carcinomas as it is for poorly differentiated ones." (PMID 35684402, 2022). "AGRN has been shown to contribute to EMT in liver and pancreatic cancer." (PMID 36358747, 2022).
Cerebral ischemia (3 papers, 2020 to 2022). Restriction of arterial blood supply to the brain associated with insufficient oxygenation to support the metabolic requirements of the tissue. "Distribution of intrathecal injection of agrin and its roles in the blood–brain barrier in a mouse model of cerebral ischemia/reperfusion are discussed." (PMID 32076591, 2020).
Colon Cancer (3 papers, 2013 to 2022). "Platelet-secreted proteins, such as agrin and thrombin-reactive protein 1, can also enhance the activity and expression of MMP-9 through the p38MAPK pathway, thereby stimulating the aggressiveness of colon cancer." (PMID 34422629, 2021).
congenital muscular dystrophy (3 papers, 2015 to 2024). A muscular dystrophy that is characterized by diminished muscle tone (hypotonia), progressive muscle weakness and degeneration (atrophy), abnormally fixed joints, spinal rigidity, and delays in reaching motor milestones such as sitting or standing unassisted. "Prior research demonstrated that the overexpression of mini-Agrin effectively mitigates dystrophic phenotypes in a laminin-α2-deficient mouse model of congenital muscular dystrophy (CMD)." (PMID 38461287, 2024). "Overexpression of a miniaturized form of Agrin could retain basal laminins and alleviate dystrophic symptoms in a mouse model of congenital muscular dystrophy (CMD)." (PMID 38461287, 2024). "It has been proven that this miniature version of Agrin could be increased expression in muscles by direct intramuscular injection and render remarkable therapeutic benefits in a mouse model of congenital muscular dystrophy." (PMID 38461287, 2024).
diabetic nephropathy (3 papers, 2010 to 2023). "Mesangial expression of perlecan and agrin was reported in human diffuse mesangial sclerosis, in diabetic nephropathy, and some other human glomerulopathies with mesangial expansion." (PMID 20140097, 2010).
gastric cancer (3 papers, 2016 to 2021). A primary or metastatic malignant neoplasm involving the stomach. "Comparing with the normal group, the signal densities of cytokines were upregulated in the MNNG-induced gastric cancer groups, including Activin A, Agrin, IL-1α (both P < 0.01), ICAM-1 (P < 0.001), and TIMP-1 (P < 0.05)." (PMID 28119756, 2016).
glioma (3 papers, 2023 to 2026). A benign or malignant brain and spinal cord tumor that arises from glial cells (astrocytes, oligodendrocytes, ependymal cells). "Cross-referencing this list with our in-house RNA-Seq dataset shows several HDACi resistance genes that are expressed at higher baseline levels in our IDHwt glioma cells, including EMP1, WWTR1, EGFR, and AGRN." (PMID 41066183, 2025).
Hepatic fibrosis (3 papers, 2018 to 2022). The presence of excessive fibrous connective tissue in the liver. "The top pathways shared across each network included LXR/RXR activation, agrin interactions at neuromuscular junctions, hepatic fibrosis, and role of osteoblasts, osteoclasts, and chondrocytes in rheumatoid arthritis." (PMID 30518872, 2018). "An IPA of these genes in the presence of rapamycin pointed to hepatic fibrosis/stellate cell activation, and HIPPO signaling in BCNS keratinocytes, whereas mitochondrial dysfunction and AGRN expression were uniquely enriched in BCNS fibroblasts." (PMID 30858923, 2019). "The global cytokine surveys of HSC-CM have demonstrated that TNF-α, agrin, PDGF, activin A, GM-CSF, IFN-γ, IL-1β, IL-4, IL-6, IL-10, IL-13, and TIMP-1, which subsequently induce acute inflammation and liver fibrosis, were elevated in aHSC-CM relative to the qHSC-CM." (PMID 36142683, 2022).
liver cirrhosis (3 papers, 2007 to 2018). "We suggest that, agrin and PDGF may prove to be the crucial targets for the treatment of liver cirrhosis and HCC, and sorafenib is one such targeted drug that has been already approved for HCC." (PMID 29285255, 2017).
melanoma (3 papers, 2021 to 2025). A malignant, usually aggressive tumor composed of atypical, neoplastic melanocytes. "For example, the predominant signaling in outgoing melanoma cells was typified by pattern 1, encompassing various pathways such as AGRN, VEGF, CD99, and others." (PMID 39781353, 2025). "This suggested that AGRN primarily acted by targeting DAG in melanoma cells." (PMID 39781353, 2025). "Notably, the AGRN signaling pathway corresponds to Melanoma cells pattern 1 and targets almost all melanoma cells, signifying its crucial role as a significant signaling pathway." (PMID 39781353, 2025). "In addition, the administration of exogenous PMEL amyloid fibrils did not increase the expression of YAP target genes upon Agrin silencing in amyloid-deficient melanoma cells (IGR39)." (PMID 38199984, 2024). "We observed that AGRN is primarily secreted by C2 PHLDA2+ Melanoma cells subgroup and C4 PCLAF+ Melanoma cells subtype, with its main target cells (receptors) were the majority of melanoma cells." (PMID 39781353, 2025). "Conversely, communication patterns of target cells indicated that incoming melanoma cell signaling was predominantly characterized by pattern 1, which including pathways such as CD99 and TNF as well as PARS, TGFb, AGRN, and MPZ." (PMID 39781353, 2025).
myasthenia (3 papers, 2013 to 2023). "In a study of 5 patients from 3 families carrying AGRN mutations, all presented with permanent distal muscle weakness and wasting in addition to myasthenia." (PMID 30808424, 2019). "Consequently, differences between patients with LRP4 myasthenia described so far and our patient with both CMS and CLS could be due to the consequences of direct binding defects of agrin to the mutated β1 propeller domain of LRP4." (PMID 37640745, 2023).
neuroblastoma (3 papers, 2008 to 2021). Neuroblastoma (NB) is the most common solid, extracranial childhood tumor. "In this particular study, a 65% reduction in AGRN gene expression was observed in rat PC12 neuroblastoma cells overexpressing Egr-1, and four putative Egr-1 binding sites were mapped to the AGRN gene promoter." (PMID 28824419, 2017). "Agrin protein expression was compared using M17 human neuroblastoma cells transfected at ~70% confluency with empty vector or a plasmid expressing human Egr-1." (PMID 28824419, 2017). "The ability of agrin to mediate cell adhesion when presented as a nanopatterned substrate was tested using neuroblastoma cell lines and agrin spaced at 60 nm." (PMID 19055842, 2008). "Adhesion of both mouse primary cortical neurons and rat B35 neuroblastoma cells showed a spacing-dependent threshold, with a sharp drop in adhesion when the space between agrin-coated nanoparticles increased from 60 to 90 nm." (PMID 19055842, 2008). "We have shown that agrin presented as a nanopatterned substrate mediates adhesion for a variety of cell types, including primary neurons and neuroblastoma cell lines." (PMID 19055842, 2008). "This provided a comparison of agrin to a homophilic adhesion molecule where both provided good adhesion for a neuroblastoma cell line." (PMID 19055842, 2008). "Based on the in-silico results, we tested whether Egr-1 bound directly to the human AGRN gene by performing ChIP using genomic Egr-1: DNA complexes extracted from human M17 neuroblastoma cells." (PMID 28824419, 2017). "Together, these data suggest that agrin protein expression is reduced as a result of increased Egr-1 expression, and that this effect results from regulation at the transcriptional level in human M17 neuroblastoma cells, rat primary neurons and mouse C2C12 myotubes." (PMID 28824419, 2017). "The results of the present study indicate that the adhesion profile of cells to patterned agrin more closely resembles that of RGD peptides than cadherins, even for neuroblastoma cell lines and primary cortical neurons." (PMID 19055842, 2008). "The insensitivity of rat B35 neuroblastoma cells to RGD peptide competition in this study is interesting and may reflect a greater dependence in this cell type for adhesion to the more C-terminal domain of agrin." (PMID 19055842, 2008).
ovarian carcinoma (3 papers, 2016 to 2024). A malignant neoplasm originating from the surface ovarian epithelium. "AGRN can be detected in ascitic fluid from patients with ovarian cancer, and is secreted by small cell lung cancer cells." (PMID 29552294, 2018). "Moreover, other genes related to the neuromuscular junction like the MuSK activator Agrin, Membralin and SLC25A1 are expressed in SKOV3WT ovarian carcinoma cells and overexpressed in SKOV3 cells exposed to cisplatin." (PMID 39592661, 2024).
prostate carcinoma (3 papers, 2021 to 2025). A carcinoma that arises from epithelial cells of the prostate gland. "The tumor-promoting function of AGRN was also demonstrated in prostate cancer." (PMID 36855119, 2023). "AGRN was also proposed as a substrate of Kallikrein-related peptidase 14 (KLK14), a serine protease involved in prostate cancer (PCa) pathogenesis." (PMID 40136513, 2025).
rectal cancer (3 papers, 2021 to 2024). A primary or metastatic malignant neoplasm that affects the rectum. "The upregulation of AGRN in rectal cancer has been shown to potentially facilitate disease progression by activating the WNT pathway." (PMID 39183444, 2024). "AGRN can elevate the activity of the WNT pathway by increasing cell cycle-related gene expression to inhibit suppressed rectal cancer cell growth." (PMID 35954210, 2022).
Sepsis (3 papers, 2017 to 2022). Sepsis is defined as life-threatening organ dysfunction caused by a dysregulated host response to infection. "A previous study conducted with a model of chronic inflammation (sepsis) showed that reduced Agrin expression contributed to abnormal expression of nAChR and caused neuromuscular dysfunction." (PMID 35103239, 2022). "The c-terminal fragment of AGRIN has been proposed as an indicator for renal function in sepsis, a biomarker for kidney transplants, and an indicator of progression of kidney disease in type 2 diabetics." (PMID 28931758, 2017).